FAM86B3P (family with sequence similarity 86 member B3, pseudogene)
Gene: Transcribed unprocessed pseudogene on chromosome 8 (8,228,605 to 8,237,275, forward strand). Ensembl gene ENSG00000173295.
Diseases named in the same sentence as FAM86B3P in open-access papers:
FAM86B3P is named in the same sentence as 1 disease in open-access papers, as found by Europe PMC text mining. Sharing a sentence is not in itself a finding about the gene and the disease.
FAM86B3P shares sentences with these, for which no sentence is quoted: schizophrenia (1 paper).